PROM1 (prominin 1)
Diseases named in the same sentence as PROM1 in open-access papers (continued):
Sharing a sentence is not in itself a finding about the gene and the disease.
tumor (continued). "Based on previous methods that we and others have employed, tumor cell populations were enriched or depleted for cancer stem cells using the stem cell marker CD133 (Prominin-1)." (PMID 19020659, 2008). "In our study, PROM1 expression was higher in tumor-like cells compared to control organoids." (PMID 40917877, 2025). "We revealed distinct spatial patterns: Lgr5-positive niches were predominantly localized in the central areas of the tumor, Alcam- and Prom1-positive niches were dispersed throughout the tumor regions, while CD44-positive niches were predominantly distributed in the outer regions." (PMID 40069574, 2025). "However, in tumor assembloids and in co-culture with organoid slices, PROM1 expression was lower than in the normal organoids or organoid slices." (PMID 40917877, 2025). "CD133 (prominin-1) is a marker of tumor-initiating cells in various solid tumors." (PMID 41426972, 2025). "Conversely, PROM1 exhibited lower levels in tumor samples compared to NATs." (PMID 40650074, 2025). "Moreover, Prom1+ cells express EMT markers in tumours generated after transplantation, suggesting that these cells have the potential for both differentiation and transdifferentiation." (PMID 40665579, 2025). "Importantly, our findings align with the first identification of prominin-1 expression within tumor cells of pseudo-palisade formations that delineate necrosis within GBM." (PMID 38258133, 2024). "Moreover, analysis of stomach tissues in the public data set of Prom1-conditional mutant mouse GC model from the GEO database (GSE40634) demonstrated significant overexpression of GNB4 mRNA in the mouse tumor tissues (P < 0.0001)." (PMID 37016382, 2023). "Prominin 1 (PROM 1, or CD133) and VEGF receptor (VEGFR)-2 double-positive endothelial progenitor cells or CD34 positive cells were observed in the stroma, suggesting tumor-associated neoangiogenesis." (PMID 35311066, 2022). "Similarly, those patients in which the tumor had high PROM1 expression and MGMT was methylated had a longer survival than unmethylated or patients with low expression of PROM1, regardless of MGMT methylation status." (PMID 36333778, 2022). "In Huh-7 HCC cell lines, epithelial cell adhesion molecule (EpCAM)- and Prominin-1 (CD133)-co-expressing cell subpopulations were shown to possess stem cell-like properties, as they frequently caused tumor development in immunocompromised NOD/SCID mice xenograft models." (PMID 36556285, 2022). "In particular, in our proteomic data, TNC was confirmed to be the most strongly upregulated matrisome protein in RETM918T-driven tumors, while it also appeared to be positively correlated with the abundance of a classical tumor stemness marker PROM1 (CD133) in Mesenchymal tumors." (PMID 36344509, 2022). "CD133 (prominin-1) is a glycosylated protein over the surfaces of the normal and cancer stem cells that contribute to the proliferation, self-renewal, differentiation, and tumor formation." (PMID 35194430, 2021). "Although HCC cells are not derived from cytokeratin 19 (Krt19) or osteopontin (Spp1) expressing biliary epithelial cells, they express higher levels of Prom1 compared to non-tumor tissues, suggesting the contribution of hepatocyte-derived PROM1+ cells in HCC formation." (PMID 33173221, 2020). "Previous studies have shown that therapies targeting PROM1 may prevent tumor development in various human cancers." (PMID 31164716, 2020). "Interestingly PROM1 a surface marker of tumor initiating cancer cells was found in both interactomes." (PMID 31024232, 2019). "In GBM-derived radioresistant tumor-initiating and PROM1-positive cell populations, ARHGAP28 was upregulated upon treatment with the anticancer compound resveratrol that resulted in induction of apoptosis and elevated radiosensitivity through repression of STAT3 pathway signaling." (PMID 31083655, 2019).
tumor (continued). "Likewise, the proportion of CD133 (Prominin-1) expressing cells varied depending on tumor and culture medium, although the density of the glycoprotein on the surface was consistently elevated after culture in serum-containing medium." (PMID 29967607, 2018). "Moreover, Prom1 is expressed in endothelial progenitor cells and contribute to the tumor vasculature in non-small cell lung cancer." (PMID 27640364, 2016). "In contrast, less than 2% of pEGFRLo tumor cells expressed Prominin-1." (PMID 27738329, 2016). "Thus, its expression seems to be preserved in tumor cells that originate from prominin-1–positive cells." (PMID 24911657, 2014). "However, when dissociated cells from proneural tumor were co-implanted with Prom1+ endothelium isolated from normal brain we found that Prom1+ endothelium was crucial to promote tumor growth." (PMID 23637986, 2013). "In our tumors, Prom1 was not only expressed by endothelium but also by large GFAP+ tumor cells." (PMID 23637986, 2013). "The first direct evidence supporting the CSC hypothesis came from the recent finding of self-renewal and tumor-initiating cells with a common and distinct surface-expressed polypeptide, the CD133 pentaspan trans-membrane glycoprotein, also known as Prominin-1." (PMID 24212791, 2011). "CD133, also known as prominin-1, is a pivotal five-transmembrane domain cell-surface glycoprotein that serves as a key biomarker for the identification and isolation of a particular subpopulation referred to as “cancer stem-like cells” across various neoplasms, including breast cancer." (PMID 40369257, 2025). "Interestingly, we observed an increase in mesenchymal signature genes, such as the adhesion molecule CD44, the PDGF receptor beta, or PPRX, and an increase in the BRCA tumor suppressor and a decrease in some classical progenitor markers, such as prominin-1 or CSMD3." (PMID 36675105, 2023). "Finally, as we compared the genes that correlated with PROM1 or PROM2 in each individual tumor type, we observed a substantial number of commonly correlated genes with the same correlation direction and we observed no commonly correlated genes with the reverse correlation direction." (PMID 31164716, 2020). "Indeed, the DRP markers such as Prom1, EpCAM, Krt19, and Sox9 detected in AH, were also induced in non-tumor liver tissue (NTL) of mice subjected to DEN injection and tumor promotion with WAD as compared to normal liver or tumor tissues, suggesting a more selective increase of DRPs in NTL." (PMID 33173221, 2020). "Therefore, downregulation of those 3 molecules (Lyve1, Prom1, Lcn2) could be responsible for lower migration capabilities of tumor (metastatic) cells in AMEC-KO mice." (PMID 27640364, 2016). "Thus, even if the CD133+ cell population was drastically reduced during the tumor development process, prominin-1 expression in tumors was still eight times higher in the CD133+ group than in tumors derived from the CD133- fraction (2.6% vs. 0.29%, respectively; n=6)." (PMID 25221643, 2014). "This raises the possibility that PROM1 may not be as closely linked with “stemness” or tumor initiating phenotype in normal cells or cancer cells as previously proposed." (PMID 25184684, 2014). "These cells, marked by proteins such as prominin-1 (CD133), SRY-box transcription factor 2 (SOX2), and polycomb complex protein BMI-1 (BMI-1), contribute to therapy resistance and tumor recurrence." (PMID 40722337, 2025). "Physiologically, the incorporation of prominin-1 into specific cholesterol-rich membrane microdomains could also explain its association or involvement in various signal transduction pathways, which regulate embryonic development, epithelial-mesenchymal transition (EMT), tumor growth and metastasis." (PMID 39881297, 2025). "CD133, also known as prominin-1, is another well-established CSC marker found in tumours of the breast, ovary, pancreas, liver, lung, stomach, and colon." (PMID 41321388, 2025).
tumor (continued). "Cells co-expressing PROM1 and CD24 have been isolated from ccRCC tumors as a small overall component of the tumor but with progenitor properties." (PMID 40558504, 2025). "Immunohistochemical staining confirmed PROM1 expression in LSCC, revealing higher levels in the paracancerous tissues compared to the tumor tissues." (PMID 39107908, 2024). "CSCs showed high expression of stem cell marker genes such as PROM1, ALDH1A1, and SOX4, and increased the activity of tumor-related hypoxia, Wnt/β-catenin, and Notch signaling pathways." (PMID 39107908, 2024). "The infiltration of CD4 and CD8 T cells, as well as the levels of the TEX marker genes (HAVCR2, TIGIT, CTLA4, LAG3, and PD1) and tumor stem cell marker genes (CD44 and PROM1), were all greater in tissue samples with high TEXSRGs-score." (PMID 37957420, 2023). "We also compared the differences in expression levels of TEX marker genes (HAVCR2, TIGIT, CTLA4, LAG3, and PD1) and the putative tumor stem cell marker genes (CD44 and PROM1) between high and low TEXSRGs-score groups in clinical tumor samples using qRT-PCR." (PMID 37957420, 2023). "Another potential target, Prominin 1 (CD133), is highly expressed in PDAC stem cells, as well as in other neoplasms." (PMID 37296886, 2023). "Other CSC markers stimulated by the Wnt/β‐catenin pathway include CD24, Prom1, CD44, and ALDH1, thereby enhancing tumor stemness." (PMID 36226253, 2022). "Genes associated with proliferation such as proliferating cell nuclear antigen (PCNA), prominin 1 (PROM1), HOP homeobox (HOPX), and olfactomedin 4 (OLFM4) were also upregulated in LPS treated IBD intestinal organoids and tumor enteroids." (PMID 35884586, 2022). "To investigate the effect of the depletion of qProm1 cells when the tumor is already formed, we electroporated newborn mice with TP-Cherry and with plasmids expressing DTA under the control of Prom1-CreERT2-p27K−." (PMID 35970913, 2022). "UMAP analysis further revealed heterogenic distribution of three liver CSC‐like markers (PROM1, EPCAM, and CD44) within tumor organoids." (PMID 34105295, 2021). "A significant increase was observed in the expression of LGR5 (p: 0.01) and PROM1 (p: 0.005) genes in villous HGD polyps, LGR5 (p: 0.003) gene in G1, and LGR5 (p: 0.0002) and MYC (p: 0.002) genes in G2 stage tumor tissues." (PMID 34452555, 2021). "Most tumors, including OSCCs, are populated with specialized oncogenic cells positive for CSC markers such as CD44, PROM1, ABCG2, and ALDH-1 and demonstrate a superior capability to develop a tumor when transplanted into other animals." (PMID 34205649, 2021). "While several progenitor genes such as SOX2 and NES were expressed broadly, PROM1 (expressed as CD133), a marker that has been shown to be sufficient to give rise to ectopic tumours, was very sparsely expressed." (PMID 34948008, 2021). "Taking advantage of the distinct origin of tumor (human) and stromal (murine) cells in our xenografts, we approached the evaluation of stemness genes NANOG, POU5F1 (OCT4), PROM1 (CD133) and SOX2, from the tumor origin." (PMID 32230715, 2020). "First, our evaluations revealed an increased gene expression of key molecules such as PROM1 (CD133) and SOX2 in tumor spheres derived from these cells whose role in endothelial trans-differentiation has been reported." (PMID 33396280, 2020). "Some studies have shown that aberrant activation of Wnt/β‐catenin in LGR5+/PROM1+/BMI‐1+ CSCs is important for CRC tumorigenesis and tumor progression in murine models." (PMID 31788944, 2020). "Epithelial cell adhesion molecule (EpCAM) and Prominin 1 (CD133) are frequently used to identify Huh-7 human HCC TICs as NOD/SCID mice developed tumor after receiving Huh-7 cells expressing these two antigens." (PMID 31366337, 2019). "Since the epithelial tumor component is the major source for the CD133 signature activity with PROM1 expression, these features will be proportional to the tumor purity and also inversely correlated with stromal signature levels." (PMID 30717708, 2019).
tumor (continued). "CD133 (prominin-1) is widely believed to be a cancer stem cell marker in various solid tumor types, and CD133 has been correlated with tumor-initiating capacity." (PMID 28687090, 2017). "The presence and number of GBM stem cells (GSCs) is one of the major factors which determine aggressiveness and treatment resistance of the tumor bulk, and surface expression of CD133 (PROM1) is regarded as a putative marker for GSCs." (PMID 29156675, 2017). "Other selected targets in clinical trials for CAR T cell therapy, an approach that also requires highly tumor-specific targets, include ERBB2, mucin-16 (MUC16), prominin 1 (PROM1) and the prolyl endopeptidase FAP (FAP)." (PMID 26700623, 2016). "We previously reported that the expression of several cancer stemness-related genes such as PROM1 (CD133), GPR49 (Lgr5) and MUC15 was significantly higher in RR cells as compared to RU cells derived from BC cell lines as well as primary tumor samples." (PMID 26683522, 2016). "Recent study has demonstrated that SCLC and NSCLC contain cells that express the glycoprotein prominin-1 (CD133), a cancer stem cell marker, which is essential for tumor cell propagation and metastasis." (PMID 25435932, 2015). "CD133 (prominin-1 or AC133) was originally described in human hematopoietic stem cells and has subsequently been used as a marker to isolate CSCs from many tumor types." (PMID 24775603, 2014). "Co-immunostaining of tumor sections with anti-ß-galactosidase and anti-CD31 antibodies revealed that a subset of Prom1+ cells in the tumors, were endothelial cells." (PMID 23637986, 2013). "In particular CD133 (Prominin 1), which is expressed on stem and early progenitor cells (CD34+ hematopoietic stem cells) and tumor-initiating cells of several malignancies, is prominent subject of ongoing research." (PMID 23915418, 2013). "On the contrary, genes of other proposed stem cell markers, such as Dcamkl-1, Msi-1 and Prom-1 (CD133), were down-regulated in DMH-tumours." (PMID 23374535, 2013). "These cells express the transmembrane glycoprotein prominin-1 (CD133) (a cell-surface marker expressed on normal human neuronal stem cell) and have the ability to initiate a tumor in vivo after xenotransplantation in mice." (PMID 23245659, 2012). "Given that the GSC state is not a stable clonal subpopulation but rather a plastic state induced by the tumor microenvironment, we scored cells based on classic GSC markers (PROM1, SOX2, NES, OLIG2, BMI1, NANOG, POU5F1) and defined the top 2% of cancer cells with the highest stemness scores as GSCs." (PMID 41041071, 2025). "However, the expression of CD133/PROM1, OCT4/POU5F1, KLF4, and MYC occurred more frequently compared to EPCAM-negative tumor spots." (PMID 39456890, 2024). "In situ sequencing also confirmed a consistent pattern: in EpCAMhigh tumor cell-dominated spots, compared to EpCAM-negative cell-dominated spots, there was a more frequent expression of the CD133/PROM1 gene along with the transcription factor genes OCT4/POU5F1, KLF4, and MYC." (PMID 39456890, 2024). "Prominin-1 (CD133) is a glycoprotein expressed on the cell membrane of stem and progenitor cells within normal tissues, and it has been proposed as a putative CSC marker across different tumor types." (PMID 37685983, 2023). "Additionally, tumor cells expressing elevated levels of the reported CSC markers NRP1, IGF1R, CD44, and PROM1 (CD133) were scattered across several clusters." (PMID 37966117, 2023). "Yet, we show here that 5-FU or cisplatin chemotherapy enrich for CD133/Prom1, suggesting that while CD133 may be proliferative, they may also harbor other mechanisms (e.g., SPINK1-mediated tumor plasticity) that enable them to resist standard chemotherapy." (PMID 38030644, 2023). "The box plot shows that the CD133 (PROM1) and CD147 (BSG) genes were significantly hypermethylated in tumors compared to normal tissues; inversely, their mRNA expression levels were downregulated in tumor tissues." (PMID 36498950, 2022).
tumor (continued). "It is tempting to speculate that STAT3- and PROM1-driven autophagy signaling pathways play key roles in modulating GBM plasticity and heterogeneity, thereby facilitating GBM tumor progression." (PMID 40396025, 2022). "Importantly, the tumor spheroids derived from the MCW-OV-SL-3 cell line expressed high levels of c-Kit, PROM1, ZEB1, SNAI, VIM, and Twist1 compared to 2D monolayer cells." (PMID 35205706, 2022). "To determine if radiation promotes vascular-like conversion of GSC or non-GSC tumor cells, we also utilized CD133 (PROM1) as a GSC marker to separate the stem-like fraction from tumor cells." (PMID 36261421, 2022). "In primary liver cancer, PROM1+ and CD47+ cancer stem cell (CSC), which was scattered in tumor areas, was found to be gradually increased from leading-edge to tumor to portal vein tumor thrombus, and closely related to TME remodeling and tumor metastasis." (PMID 36313703, 2022). "Other intestinal stem cell markers and genes associated with proliferation, notably proliferating cell nuclear antigen (PCNA), prominin 1 (PROM1), HOP homeobox (HOPX), and olfactomedin 4 (OLFM4), were also increased in LPS-treated IBD intestinal organoids and tumor enteroids." (PMID 35884586, 2022). "For the castration-induced regression nadir group (i.e., those with the weakest or most unsuccessful castration-induced tumor regression), GSE1, CYP3A5, CTNNB1, CYP3A4, POU5F1, ABCB1, alkaline phosphatase liver/bone/kidney isozyme (ALPL), PROM1/CD133, ABCG2, and SOX2 were concomitantly upregulated." (PMID 34439112, 2021). "Furthermore, increases in the properties of stem cells were measured by assessing the capacity for tumor formation and performing transcriptional analysis of the OSKM genes (OCT4, SOX2, KLF4 and MYC), NANOG, NES and PROM1." (PMID 34364391, 2021). "Another putative CSCs marker is prominin-1, also called CD133, which is a five transmembrane domain glycoprotein with unknown function that behaves as a stemness marker in many normal and tumor cells." (PMID 33916320, 2021). "Some of the tumor cells expressed stem cell markers (e.g., PROM1) but did not form separate clusters." (PMID 32988401, 2020). "Yet, biallelic Prom1 knock-in mice which lack Prom1 expression, still developed liver tumors as WT mice, suggesting that PROM1 is a pivotal marker for DRPs/TICs which generate tumor cells while PROM1 itself is not required for tumor development." (PMID 33173221, 2020). "In addition, PROM1 expression and ALDH activity of tumor spheroids were downregulated upon Mit-A treatment demonstrating a direct suppressive effect on cancer cell stemness." (PMID 33240813, 2020). "In addition, several studies have shown that PROM1 and PROM2-targeted therapies are promising for the prevention of tumor development." (PMID 31164716, 2020). "Some of these genes, which interfere with tumor cell growth/differentiation/migration/invasion (such as MYC, MET, PROM1, and PTK2), induce hypoxia (such as ARNT2, HIF3A, TGB2, MMP2, and POSTN) and genes regulating transcription via acetylation were downregulated upon pembrolizumab treatment." (PMID 32616706, 2020). "Radiotheranostic targeting of colorectal CSCs using Prominin 1 (PROM1; known as CD133) and CD44 monoclonal antibodies labeled with radioodine led to a significant inhibition of tumor growth and prolonged mean survival of xenografted mice injected with HT29 CRC cell line." (PMID 33240813, 2020). "Early in vivo studies demonstrated that a subpopulation of tumor cells expressing CD133 (Prominin-1) antigen was capable of tumor initiation when implanted into the adult NOD-SCID (non-obese diabetic, severe combined immunodeficient) mouse brains." (PMID 31387280, 2019). "Expression of putative stem cell markers CD15 and CD133 (Prominin-1) varied with tumor type, independent of medium conditions." (PMID 29967607, 2018).